GAS5 (growth arrest specific 5)
Diseases named in the same sentence as GAS5 in open-access papers (continued):
Sharing a sentence is not in itself a finding about the gene and the disease.
osteoporosis (continued). "In other studies, GAS5 expression had altered in patients with osteoporosis." (PMID 35155450, 2021). "In addition to its roles in the GAS5/SMAD7 and GAS5/miR-135a-5p/FOXO1 axes, GAS5 also had other regulatory effects in osteoporosis." (PMID 35155450, 2021). "For instance, lncRNA growth arrest-specific transcript 5 (GAS5) may improve osteoporosis through accelerating MSC osteogenic differentiation via the microRNA (miR)-498/runt-related transcription factor 2 (RUNX2) axis." (PMID 34772438, 2021). "GAS5 has also been shown to have key functions in osteoporosis." (PMID 35155450, 2021). "The GAS5 expression level is significantly downregulated in patients with osteoporosis." (PMID 35155450, 2021). "Considering all of these findings together, we concluded that GAS5 is a critical molecule in the osteoblast and adipocyte differentiation and contributes to the pathogenesis of osteoporosis, emphasizing its novel role in the diagnosis and treatment of this disease." (PMID 33006314, 2020). "In our research, we found that the level of GAS5 expression was decreased in the bone tissue and BMSCs of osteoporosis patients, indicating that GAS5 may be related to the progression of osteoporosis." (PMID 33006314, 2020). "GAS5 decreased in osteoporosis and positively correlated with the osteoblast differentiation." (PMID 33006314, 2020). "To confirm this hypothesis, we constructed a global Gas5 knockout mouse model to explore the role of GAS5 in osteoporosis." (PMID 33006314, 2020). "Taken together, these results suggest that Gas5 may be a promising therapeutic target in osteoporosis." (PMID 33006314, 2020). "The mRNA level of GAS5 in both bone tissues and BMSCs was decreased in patients with osteoporosis compared to in those with hip dysplasia and normal control, which indicated that GAS5 expression was closely related to bone metabolism in osteoporosis." (PMID 33006314, 2020). "In conclusion, we found that GAS5 acts as a protective target in osteoporosis." (PMID 33006314, 2020). "Moreover, a decreased bone mass and impaired bone repair ability were observed in Gas5 heterozygous mice, manifesting in osteoporosis." (PMID 33006314, 2020). "A novel lncRNA GAS5 could alleviate osteoporosis progression by suppressing the miR-498/RUN2 axis." (PMID 35226820, 2022). "In addition, lncRNA GAS5 is up-regulated in osteoporosis and may down-regulate miR-21 to promote osteoclast apoptosis." (PMID 34583640, 2021). "Targeting GAS5 may greatly contribute to both the diagnosis and treatment of osteoporosis." (PMID 33006314, 2020). "The GAS5/SMAD7 axis and GAS5/miR-135a-5p/FOXO1 axis in MSCs are both involved in the development and prognosis of osteoporosis and will be described in greater detail in Section 4.1." (PMID 35155450, 2021). "In conclusion, GAS5 promotes osteoblast differentiation by targeting the UPF1/SMAD7 axis and protects against osteoporosis." (PMID 33006314, 2020). "According to another study, an lncRNA, growth arrest-specific 5 (GAS5), was also present at a low concentration in osteoporosis patients and could also upregulate Runx2." (PMID 33281877, 2020). "For example, the researches of Wang, X etc. indicated that Gas5 could promotes osteogenic differentiation of bone marrow mesenchymal stem cells by FOXO1 in mouse.However, the effect of GAS5 on human osteoblast differentiation and its role in osteoporosis have not been clearly clarified." (PMID 33006314, 2020).
colon carcinoma (11 papers, 2017 to 2024). "lncRNA GAS5 contributes to lymphatic metastasis and was significantly associated with the susceptibility and progression of colon cancer." (PMID 30984308, 2019). "In conclusion, the present study demonstrates that lncRNA GAS5 plays a tumor-suppressive role in colon cancer cells." (PMID 36672566, 2022). "GAS5 was found to be downregulated in colon cancer cell lines that are resistant to 5-fluorouracil (5-FU)." (PMID 36672566, 2022). "Our findings suggest that GAS5 plays a key role in the regulation of anti-cancer drug resistance in colon cancer and has therapeutic potential for effective chemotherapy." (PMID 36672566, 2022). "The relative expression of GAS5 was significantly lower in three different resistant colon cancer cell lines, including SNU-C4R, SNU-C5R, and HCT116R, compared to their parental cells." (PMID 36672566, 2022). "From our literature review, we found that several lncRNAs among the ceRNA network, such as lncRNAs UCA1, GAS5, MALAT1, and PVT1, are associated with oncogenesis and the development of colon cancer." (PMID 30984308, 2019). "The expression of GAS5 was significantly downregulated in the colon carcinomas compared to paired-adjacent normal tissues of 24 patients with sporadic CRC." (PMID 28099146, 2017). "Functional investigations of rs55829688 reveal that genotypes of this variant were able to regulate the expression levels of GAS5 in peripheral blood and colon cancer cells through altered binding affinities of GAS5 promoter with the transcription factor p63 53 and Yin Yang-1 41, respectively." (PMID 39239549, 2024). "Furthermore, we have previously observed the reduction of GAS5 in 5-FU resistant colon cancer cells." (PMID 36672566, 2022). "GAS5 overexpression may be helpful to combat metastasis or drug response of drug-resistant colon cancer cells." (PMID 36672566, 2022). "In this study, the role of GAS5 in 5-FU resistance was investigated in human colon cancer cells." (PMID 36672566, 2022). "Subsequently, we found that the expression level of miR-21 in human colon cancer cell lines was lower than the normal cell lines and knockdown of GAS5 could increase the expression level of miR-21, and GAS5 could bind with miR-21 in vivo." (PMID 36062165, 2022). "It is found that GAS5 is positively correlated to colon cancer as well." (PMID 33745450, 2021). "Our previous study using human colon cancer cells (SNU-C4 and SNU-C5) and their 5-FU resistant cells (SNU-C4R and SNU-C5R) revealed lncRNA GAS5 as one of the downregulated lncRNAs in the resistant cells." (PMID 36672566, 2022). "In our current study, we found that the expression of GAS5 in tumor tissues was significantly lower than in adjacent tissues in CRC, and it was the same for some human colon cancer cell lines when compared with the normal." (PMID 36062165, 2022). "In this study, we also demonstrated the competitive relation between GAS5 and miR-128-3p on BAX regulation and its contribution as a ceRNA in anti-cancer drug resistance of colon cancer cells." (PMID 36672566, 2022). "We demonstrate that lncRNA GAS5 enhances BAX expression by interfering with miR-128-3p, thereby contributing to decreasing resistance of colon cancer cells in response to anti-cancer drugs." (PMID 36672566, 2022). "As to colon cancer, several lncRNAs are revealed to regulate colon cancer cells proliferation, apoptosis, migration, invasion, chemoresistance, and so on, such as lncRNA N-BLR, GAS5, HNF1A-AS1, CRNDE, LINC01133." (PMID 30530918, 2018).
coronary artery disease (11 papers, 2019 to 2025). "Clinical analyses of coronary artery disease cohorts reveal inverse regulatory relationships between lncRNA GAS5 and miR-21 expression profiles." (PMID 40563948, 2025). "In addition, lnc-GAS5 is involved in the development of atherosclerosis and coronary heart disease (CHD), with miR-21 as its target." (PMID 40243658, 2025). "One plasma GAS5 has been applied as a novel biomarker for coronary artery disease." (PMID 33047847, 2020). "Furthermore, other studies have found significantly lower plasma GAS5 in patients with coronary artery disease (CAD), suggesting its downregulation could serve as a relatively specific biomarker for the condition." (PMID 40563948, 2025).
Sepsis (11 papers, 2021 to 2026). Sepsis is defined as life-threatening organ dysfunction caused by a dysregulated host response to infection. "We evaluated the expression levels of several lncRNAs implicated in sepsis progression, including growth arrest‐specific 5 (Gas5), the RNA component of mitochondrial Rmrp, and SOX2 overlapping transcript (Sox2ot), in AEC‐IIs and their derived exosomes." (PMID 41178622, 2026). "Lnc‐GAS5 relates to Th17 cells and serves as a potential biomarker for sepsis severity and mortality risk." (PMID 35325494, 2022). "Moreover, GAS5 knockdown in early sepsis caused a surge in lung ROS levels, whereas GAS5 overexpression reduced ROS levels." (PMID 37509452, 2023). "Besides, a logistic regression analysis was also performed, which showed that lnc‐GAS5 was an independent factor in predicting the sepsis risk." (PMID 35325494, 2022). "In conclusion, lnc‐GAS5 relates to Th17 cells, and serves as a potential biomarker for sepsis‐induced multi‐organ injury and mortality risk; therefore, helps the clinicians to stratify the sepsis patients and individualize their treatment." (PMID 35325494, 2022). "Sepsis may be accompanied with hypotension and hypoperfusion, while high expression of GAS5 has been found to be linked with hypoxia-induced cardiomyocyte apoptosis." (PMID 33645622, 2021). "In fact, the case of sepsis particularly demonstrates this complexity, with GAS5 potentially playing different roles in inflammation modulation depending on the disease stage and cellular context, making GAS5 manipulation in this case particularly complicated." (PMID 39941145, 2025). "GAS5 has recently been demonstrated, in varying models, to have a multifaceted role in its involvement in inflammatory responses and mechanisms in sepsis." (PMID 39941145, 2025). "In sepsis-associated AKI, GAS5 limits tubular pyroptosis by regulating miR-579-3p and activating the SIRT1–PGC-1α–Nrf2 pathway." (PMID 41303683, 2025). "The case of sepsis adds complexity, where GAS5’s dual role, suppressing or encouraging inflammation in what appears to be a timing- and cell-dependent manner, offers potential opportunities for finely tuned therapeutic interventions." (PMID 39941145, 2025). "Another study implicates GAS5 as a key suppressor of inflammatory responses in sepsis through the modulation of the miR-155-5p/SIRT1/HMGB1 axis." (PMID 39941145, 2025). "The evaluation of ROS levels in lung tissue also showed that lung tissue with a high expression of MITF or GAS5 showed lower ROS levels under sepsis, while lung tissue overexpressing miR-23 displayed noticeably higher ROS levels." (PMID 37509452, 2023). "The expression of GAS5 alleviated the inflammatory factor- or ROS-induced remodeling of intercellular junctions, reducing sepsis-induced pulmonary vascular leakage." (PMID 37509452, 2023). "Our examination of the effect of GAS5 revealed that it can inhibit oxidative stress and maintain mitochondrial homeostasis, ultimately leading to the attenuation of lung injury in sepsis." (PMID 37509452, 2023). "Our findings suggested a potential link between sepsis-induced GAS5 expression and the protective autophagy mechanism triggered by oxidative stress." (PMID 37509452, 2023). "Our studies with CLP-induced sepsis model mice revealed elevated GAS5 expression in the vascular endothelium." (PMID 37509452, 2023). "While the role of GAS5 in sepsis-induced organ injury has been increasingly acknowledged, the existing literature seems to slightly overlook the exploration of the upstream regulatory mechanisms that induce GAS5 expression." (PMID 37509452, 2023). "HE staining revealed that GAS5 mitigated sepsis-induced vascular leakage, reduced lung injury, and preserved lung tissue structural integrity." (PMID 37509452, 2023). "In vivo, GAS5 reduced tissue ROS levels, maintained vascular barrier function to reduce leakage, and ultimately attenuated sepsis-induced lung injury." (PMID 37509452, 2023).
Sepsis (continued). "Methods and results: We observed that GAS5 expression in the endothelium was significantly upregulated in a sepsis mouse model." (PMID 37509452, 2023). "In summary, the protective effect of GAS5 in sepsis is mainly the result of the synergistic effect of the target gene transcribed by MITF." (PMID 37509452, 2023). "Therefore, sepsis may cause the downregulation of GAS5 and miR-146a." (PMID 35112981, 2022). "Long noncoding RNA GAS5 (lnc‐GAS5) is able to regulate macrophage M1 polarization and Th17 cell differentiation, also engaged in sepsis‐induced inflammation and organ injury." (PMID 35325494, 2022). "Another study indicates that lnc‐GAS5 aggravates myocardial depression in mice with sepsis via the microRNA‐449b/HMGB1 axis and the NF‐κB signaling pathway." (PMID 35325494, 2022). "One hundred‐one sepsis patients were enrolled for detecting lnc‐GAS5, Th1 cells, Th17 cells, IFN‐γ and IL‐17A." (PMID 35325494, 2022). "Lnc‐GAS5 was reduced in sepsis patients than in HCs (p < 0.001), which also well‐distinguished sepsis patients from HCs with AUC 0.860." (PMID 35325494, 2022). "Firstly, the lnc‐GAS5 was only detected after the enrollment of all subjects, while its multi‐time point detection to monitor the progression of sepsis patients was needed and should be conducted in further study." (PMID 35325494, 2022). "This study was carried out to study the crosstalk between GAS5 and miR-146a in sepsis-induced acute lung injury (sepsis-ALK)." (PMID 35112981, 2022). "lncRNA GAS5 promotes sepsis-induced myocardial depression via the miR-449b/HMGB1 axis and the following NF-κB activation." (PMID 35720285, 2022). "The close correlation between GAS5 and miR-146a in sepsis-ALI indicates a potential interaction between them." (PMID 35112981, 2022). "In the present study, we showed that lnc‐GAS5 was decreased in sepsis deaths compared with sepsis survivors, also, it had an ability in estimating the 28 days mortality in sepsis." (PMID 35325494, 2022). "We found that GAS5 and miR-146a were downregulated in sepsis-ALI and the expression of these two were correlated." (PMID 35112981, 2022). "Overexpression of GAS5 exacerbated the impairment in mouse heart function in mice with sepsis, while PDTC alleviated the symptoms and led to tissue structure recovery (all P<0.01)." (PMID 33645622, 2021). "Activity of NF-κB signaling was evaluated, and NF-κB inhibition was induced in mice with sepsis and overexpression of GAS5." (PMID 33645622, 2021). "Then we found the MAP, LVSP and ±dp/dtmax values were evidently up-regulated following GAS5 inhibition, indicating heart function of mice with sepsis was partly recovered, and the myocardial depression/injury was reduced." (PMID 33645622, 2021). "Next, artificial inhibition or overexpression of GAS5 was introduced via transfecting LV-GAS5-shRNA or LV-GAS5 vectors into the myocardial tissues of rats with sepsis." (PMID 33645622, 2021). "The study aims to figure out the role of long non-coding RNA (lncRNA) GAS5 in the myocardial depression in mice with sepsis." (PMID 33645622, 2021). "Recently, others have hypothesized that GAS5 may have a dual role in sepsis, promoting inflammation in early stages and inhibiting excessive inflammatory damage in later stages through different mechanisms." (PMID 39941145, 2025). "Altogether, the context-dependent nature of GAS5 and its interaction with miRNA axes in sepsis highlights its complex role, exhibiting protective effects in some cellular environments while exacerbating inflammation and apoptosis in others, potentially influenced by timing and cell-specific factors." (PMID 39941145, 2025). "Furthermore, Zeng and associates discovered that lncRNA GAS5 forms a regulatory axis with miR-155-5p/SIRT1/HMGB1 in sepsis, with lncRNA GAS5 upregulating SIRT1 to suppress HMGB1 acetylation and release." (PMID 38690282, 2024).
Sepsis (continued). "The selective regulation of autophagy by GAS5 under oxidative stress has developed the theory of sepsis-related autophagy regulation, and the biological role of GAS5 in anti-oxidation and anti-inflammation also suggests that GAS5 is expected to become a new target for the treatment of sepsis." (PMID 37509452, 2023). "This illustrates another dimension of GAS5’s role in organ-specific responses to sepsis." (PMID 37509452, 2023). "Overall, GAS5, functioning as an antioxidant and anti-inflammatory lncRNA, may provide a promising target in sepsis." (PMID 37509452, 2023). "The continuous downregulation of GAS5 and miR-146a may in turn result in the development of lung injury in sepsis patients." (PMID 35112981, 2022). "Lnc‐GAS5 decreased in died sepsis patients compared to survivors." (PMID 35325494, 2022). "Finally, lnc‐GAS5 was decreased in dead sepsis patients compared to survivors (p = 0.007), which also distinguished sepsis deaths from survivors with AUC 0.713." (PMID 35325494, 2022). "Moreover, the decreases in the expression levels of GAS5 and miR-146a were higher in sepsis-ALK patients in comparison to that in sepsis patients." (PMID 35112981, 2022). "The correlation of lnc‐GAS5 with mortality in sepsis patients is also of great concern." (PMID 35325494, 2022). "Our data illustrated that GAS5 and miR-146a were both downregulated in sepsis-ALK." (PMID 35112981, 2022). "GAS5 and miR-146a were downregulated in sepsis-ALK and GAS5 may decrease miR-146a gene methylation to upregulate miR-146a, thereby decreasing the apoptosis of HBEpCs induced by LPS." (PMID 35112981, 2022). "Therefore, GAS5 is downregulated in sepsis-ALI and inhibits cell apoptosis by up-regulating the expression of miR-146a." (PMID 35112981, 2022). "The crosstalk between GAS5 and miR-146a in sepsis-ALK was investigated." (PMID 35112981, 2022). "Sixthly, the number of sepsis deaths was low, thus the statistical power of data about the comparison of lnc‐GAS5 between septic survivors and septic deaths might be insufficient, which should be validated in a larger‐sample‐size study." (PMID 35325494, 2022). "Therefore, the correlation between GAS5 and miR-146a across sepsis-ALI, sepsis and the control samples were analyzed." (PMID 35112981, 2022). "Lnc‐GAS5 negatively linked with Th17 cells and IL‐17A; negatively correlated with SOFA score, SOFA‐Respiratory system score, SOFA‐Coagulation score and SOFA‐Renal system score; negatively related to CRP and APACHE II score in sepsis patients." (PMID 35325494, 2022). "Our study suggested that GAS5 might promote sepsis-induced myocardial depression via the miR-449b/HMGB1 axis and the following NF-κB activation." (PMID 33645622, 2021). "The RT-qPCR identified that GAS5 is highly expressed in mice with sepsis (P<0.01)." (PMID 33645622, 2021). "Combining the results that the NF-κB inhibitor PDTC partially alleviated the myocardial injury induced by overexpression on GAS5, it could be inferred that the NF-κB activation might be responsible for GAS5-induced myocardial depression following sepsis." (PMID 33645622, 2021). "Herein, we identified one of the differentially expressed lncRNAs, GAS5 after sepsis, and then measured whether GAS5 participates in the myocardial depression in mouse models, and had the further mechanisms explored." (PMID 33645622, 2021). "Therefore, GAS5 and miR-146a may serve as potential targets to improve the conditions of sepsis-ALK patients." (PMID 35112981, 2022). "However, we observed the significant correlation between GAS5 and miR-146a only across sepsis-ALK." (PMID 35112981, 2022). "Therefore, the reduction of GAS5 and miR-146a in lung tissues of sepsis-ALK patients may significantly affect their expression levels in plasma." (PMID 35112981, 2022). "In addition, GAS5 and miR-146a were also downregulated in sepsis patients (p < 0.05)." (PMID 35112981, 2022).